GRK2 (G protein-coupled receptor kinase 2)
Diseases named in the same sentence as GRK2 in open-access papers (continued):
Sharing a sentence is not in itself a finding about the gene and the disease.
Cognitive impairment (2 papers, 2009 to 2020). Abnormal cognition is characterized by deficits in thinking, reasoning, or remembering. "Lymphocyte G-protein coupled receptor kinase 2 (GRK2) protein, a biomarker of sympathetic dysfunction, is highly expressed in patients with AD, correlating with the severity of cognitive impairment." (PMID 32650427, 2020).
cystic fibrosis (2 papers, 2021). Autosomal recessive disorder caused by pathogenic variants in the CFTR gene (cystic fibrosis transmembrane conductance regulator), which encodes a chloride and bicarbonate channel expressed in epithelial cells, and follow the diagnosis criteria. "Its expression however is altered during pathological conditions; for e.g., the expression levels of GRK2 is enhanced in cystic fibrosis patients." (PMID 35386975, 2021). "In addition, GRK2 is upregulated in the lungs of the cystic fibrosis patients and this correlated with decreased β2AR expression and activity in these individuals." (PMID 35386975, 2021). "In the cystic fibrosis tissues, there is a higher expression of GRK2 by Western blot." (PMID 35111168, 2021).
experimental autoimmune encephalomyelitis (2 papers, 2018 to 2025). An autoimmune demyelinating disease of the central nervous system that is produced experimentally in animals by the injection of homogenized brain or spinal cord in Freund's adjuvant. "For example, the expression of GRK2 was reduced in splenocytes in the rats with experimental autoimmune encephalomyelitis (EAE), an animal model of relapsing-remitting multiple sclerosis (MS)." (PMID 29922165, 2018).
gallbladder cancer (2 papers, 2019 to 2023). "Previous studies have shown that in gallbladder cancer cells, eIF3d leads to tumour progression via stable expression of G-protein coupled receptor kinase 2 (GRK2) and activation of the phosphatidylinositol 3-kinase (PI3K)-AKT signalling pathway." (PMID 31118081, 2019). "Furthermore, immunohistochemical staining showed that GRK2 expression correlated with eIF3d in human gallbladder cancer specimens, consistent with the possible eIF3d regulation of GRK2 expression." (PMID 36997088, 2023).
glioblastoma (2 papers, 2013 to 2023). The most malignant astrocytic tumor (WHO grade IV). "For example, PDGFR/Src has been shown to regulate GRK2 activity in other cell types and the suppression of GRK3 appears necessary for maximal glioblastoma cell growth." (PMID 23497290, 2013).
glioma (2 papers, 2012 to 2019). A benign or malignant brain and spinal cord tumor that arises from glial cells (astrocytes, oligodendrocytes, ependymal cells). "Here, we review data pertaining to potential molecular interaction partners of ezrin in astrocytes, with a focus on PKC and GRK2, and in gliomas and other diseases, to stimulate further research on their potential roles in glia-synaptic physiology and pathology." (PMID 31382374, 2019).
hepatocellular carcinoma (2 papers, 2015 to 2021). A malignant tumor that arises from hepatocytes. "GRK2 can also repress the serum-, insulin-like growth factor 1 (IGF1)-, angiotensin (Ang)II-, tumor necrosis factor (TNF) α- or PDGF-induced proliferation and migration of thyroid cancer cell lines, human hepatocellular carcinoma cells and smooth muscle cells, respectively." (PMID 34335610, 2021).
hyperaldosteronism (2 papers, 2019 to 2020). Overproduction of aldosterone by the adrenal glands, which may lead to hypokalemia and/or hypernatremia. "This suggests that adrenal GRK2 may be a molecular link connecting the sympathetic nervous and renin-angiotensin systems at the level of the adrenal cortex and that its inhibition might be therapeutically advantageous in hyperaldosteronism-related conditions." (PMID 31963151, 2020). "Our study reveals that GRK2 activity is a critical player downstream of the aldosterone signaling pathway; therefore, inhibiting this kinase is an attractive strategy to prevent the cardiac structural disarray and dysfunction that accompany any clinical condition accompanied by hyperaldosteronism." (PMID 31447681, 2019).
Impaired glucose tolerance (2 papers, 2011 to 2018). An abnormal resistance to glucose, i.e., a reduction in the ability to maintain glucose levels in the blood stream within normal limits following oral or intravenous administration of glucose. "To confirm the clinical observation, we also studied MIF expression in prediabetic rats with impaired glucose tolerance (IGT) and relationship between MIF and GRK2 expression in H9C2 cardiomyoblasts exposed to high glucose." (PMID 21283592, 2011).
influenza (2 papers, 2018 to 2019). An acute viral infection of the respiratory tract, occurring in isolated cases, in epidemics, or in pandemics; it is caused by serologically different strains of viruses (influenzaviruses) designated A, B, and C, has a 3-day incubation period, and usually lasts for 3 to 10 days. "While further in vivo studies using more potent GRK2 inhibitors will be needed to fully assess the potential of GRK2 inhibition as therapeutic option, our results establish GRK2 as novel drug target candidate for influenza." (PMID 30206219, 2018).
injury (2 papers, 2020 to 2024). Damage inflicted on the body as the direct or indirect result of an external force, with or without disruption of structural continuity. "In our previous study, induced pluripotent stem cells could downregulate neutrophil chemotaxis in endotoxin-induced acute lung injury, an effect associated with the enhancement of GRK2 activity and the reduction of CXCR2 expression." (PMID 32630825, 2020).
left ventricular hypertrophy (2 papers, 2021 to 2023). Enlargement of the LEFT VENTRICLE of the heart. "A synthetic peptide inhibitor of GRK2 designed as the catalytic domain of GRK2 linked to the antennapedia internalization sequence (Ant124) prevented left ventricular hypertrophy and inhibited NF-κB expression in an experimental model." (PMID 34884857, 2021).
liver fibrosis (2 papers, 2021 to 2023). "Among these mechanisms, the association between G protein-coupled receptor kinase 2 (GRK2), an inhibitor of G protein-coupled receptor signaling, and Akt-mediated endothelial nitric oxide synthase (eNOS) activation has been reported in experimental models of liver fibrosis." (PMID 38075169, 2023). "In the future research, we must pay more attention to potential role and mediated mechanisms of GRK2 in liver fibrosis." (PMID 35111168, 2021). "In addition, experiments also find lower GRK2 expression can promote the proliferation of HSCs and promote the occurrence of liver fibrosis." (PMID 35111168, 2021). "It suggested that GRK2 may also slow down the process of liver fibrosis by desensitizing A2AR in fibrotic tissue." (PMID 35111168, 2021).
malaria (2 papers, 2010 to 2012). Malaria is a serious and sometimes fatal disease caused by a parasite that commonly infects a certain type of mosquito which feeds on humans. "Phagocytic activity, superoxide production, chemotaxis and the presence of G protein-coupled receptor (GRK2) were also evaluated in neutrophils from malaria patients." (PMID 22745844, 2012). "Interestingly, neutrophils from the malaria patients expressed high levels of GRK2, low levels of CXCR2, and displayed impaired chemotaxis towards IL-8 (CXCL8)." (PMID 22745844, 2012). "Thus, decreased expression of CXCR2 and CD88 on neutrophils from malaria patients may be a consequence of an enhanced expression of GRK2." (PMID 22745844, 2012).
metabolic syndrome (2 papers, 2018 to 2021). A cluster of metabolic risk factors for CARDIOVASCULAR DISEASES and TYPE 2 DIABETES MELLITUS. "Overall, while excessive GRK2 signaling appears to both contribute to the establishment of IRES, HTN and metabolic syndrome, the absence of GRK2 also affects endothelial homeostasis, demonstrating the physiological role of the kinase." (PMID 33467677, 2021).
neuroblastoma (2 papers, 2017 to 2023). Neuroblastoma (NB) is the most common solid, extracranial childhood tumor. "Additionally, we employed the human neuroblastoma SH-SY5Y cell line as an in vitro model of dopaminergic neurons with which to investigate the interaction between endogenous GRK2 and D2R upon the stimulation of the β-arrestin signaling pathway after pretreatment with the Src kinase inhibitor PP2." (PMID 37373182, 2023).
pancreas cancer (2 papers, 2015 to 2024). "As an example to demonstrate the validity of this approach, comprehensive data on previously unknown functions of one candidate gene selected through this process (ADRBK1/GRK2) in pancreatic cancer cells is presented." (PMID 25849100, 2015). "As an example to demonstrate the validity of the approach, comprehensive functional data on candidate gene ADRBK1/GRK2, which has previously not been implicated in pancreatic cancer, is presented." (PMID 25849100, 2015).
preeclampsia (2 papers, 2021 to 2024). Preeclampsia is a hypertensive disorder of pregnancy that is characterized by new-onset hypertension with proteinuria presenting after 20 weeks of gestation, and depending on mild or severe forms may initially present with severe headache, visual disturbances, and hyperreflexia. "Insufficient GRK2 activity compromises spiral artery remodeling and initiates necrotic events in the placenta, thereby causing preeclampsia." (PMID 38961282, 2024). "To see if the down-regulation of trophoblastic GRK2 levels was intimately associated with the pathogenesis of preeclampsia, we set up experiments on pregnant mice." (PMID 34917606, 2021). "For example, elevated GRK2 levels in the umbilical vasculature are associated with elevated blood pressure in subjects with gestational hypertension and preeclampsia, but this may be a compensatory rather than a causative effect." (PMID 38961282, 2024). "Together, our findings demonstrated that insufficient GRK2 activity compromises spiral artery remodeling and initiates necrotic events in placentae, thereby leading to preeclampsia." (PMID 34917606, 2021). "Hence, these observations emphasized the crucial roles of GRK2 in the pathogenesis of preeclampsia by initiating trophoblast necroptosis and interfering with the trophoblastic invasion ability." (PMID 34917606, 2021). "Mice from the 4 mg/kg and GRK2-LV group developed elevated blood pressure from E14.5 to E18.5 (had surged over 20 mmHg compared to early pregnancies), which closely resembled the late gestational hypertension in pre-eclamptic women." (PMID 34917606, 2021). "However, insufficient research has evidenced the potential roles of GRK2 in preeclampsia until now." (PMID 34917606, 2021). "The absence of GRK2 in trophoblasts, could initiate trophoblast necroptosis, attenuate transformation of spiral arteries, and lead to late-gestational hypertension and proteinuria." (PMID 34917606, 2021).
primary Sjögren's syndrome (2 papers, 2022 to 2025). "Recently, paeoniflorin-6’-O-benzene (CP-25) has been found to limit the target organ index and B cell activities in experiment Sjögren’s syndrome (ESS) by inhibiting CXCR5-G protein-coupled receptor kinase 2 (GRK2)-ERK/p38 signaling pathway." (PMID 35309354, 2022).
abdominal aortic aneurysm (1 paper, 2020). Enlargement and ballooning of the vessel that supplies arterial blood to the abdomen, pelvis and legs. "The positive correlation between GRK2 levels and macrophage- and lymphocyte-specific markers in PVAT of patients with abdominal aortic aneurysms highlights the importance of GRK2 in immune cells in this specific adipose tissue depot." (PMID 33020373, 2020). "GRK2 expression positively correlates with myeloid- (CD68) and lymphoid-specific (CD3, CD4, and CD8) markers and with leptin in PVAT from patients with abdominal aortic aneurysms." (PMID 33020373, 2020).
airway hyperresponsiveness (1 paper, 2021). "We observed a significant reduction of airway hyperresponsiveness (AHR), lung eosinophil and lymphocyte counts, serum IgE, Th2 cytokines (IL-4 and IL-13), goblet cell hyperplasia and mucus production in mice that had reduced GRK2 expression specifically in T cells." (PMID 35386975, 2021).
allergic contact dermatitis (1 paper, 2023). An inflammatory skin condition caused by an immune response to direct contact between the skin and an allergen. "Topical glutamine administration was shown to inhibit scratch behavior in an animal model of allergic contact dermatitis via the G-protein coupled receptor kinase (GRK-2)." (PMID 36816714, 2023).
amyotrophic lateral sclerosis (1 paper, 2009). Amyotrophic lateral sclerosis (ALS) is a neurodegenerative disease characterized by progressive muscular paralysis reflecting degeneration of motor neurons in the primary motor cortex, corticospinal tracts, brainstem and spinal cord. "Finally, neurodegeneration can have numerous overlapping features, and GRK2 along with the action of specific phosphatases has been implicated in other neurodegenerative diseases such as amyotrophic lateral sclerosis (ALS)." (PMID 20204079, 2009).
Arrhythmia (1 paper, 2023). Any cardiac rhythm other than the normal sinus rhythm. "Although several findings indicate that GRK2 is capable of controlling ATP and ROS generation, metabolic stress, and mitochondrial dynamics, the precise role of GRK2 in arrhythmias remains to be unraveled." (PMID 36899814, 2023).
asthma (1 paper, 2021). "GRK2 is a ubiquitously expressed serine/threonine kinase that has been previously reported to control the activities of different cell types associated with the asthma pathology." (PMID 35386975, 2021). "Given that the Th2 cytokines (IL-4 and IL-13) are reduced in the lungs of GRK2+/− mice, it is possible that GRK2 modulates T cell responses during asthma." (PMID 35386975, 2021). "Our data thus suggests that GRK2 plays an important role in promoting T lymphocyte responses in asthma." (PMID 35386975, 2021). "While all of these previous studies implicate a role for GRK2 in possibly regulating the asthma pathology, our current study is the first to test this contention." (PMID 35386975, 2021). "In the current study, we observed that GRK2 levels are enhanced in the lungs of human asthma patients and in mice sensitized to house dust mite extract (HDME) allergen." (PMID 35386975, 2021). "To test if GRK2 levels are affected in a mouse model of human asthma, we treated wild-type B6 mice with HDME on alternative days (for a total of seven exposures) and harvested the lung tissue 24 h following the final exposure." (PMID 35386975, 2021). "Because Th2 cells are the major source of these cytokines during asthma, we determined the role of GRK2 in regulating T cell-specific responses in our HMDE mouse model." (PMID 35386975, 2021). "Further studies clarifying the mechanism through which GRK2 regulates T cell responses will help usher in a new approach for clinical management of asthma symptoms in patients that are resistant to corticosteroid therapy." (PMID 35386975, 2021). "To determine if GRK2 is similarly upregulated in the lungs during asthma, we performed qRT-PCR and IHC staining on lung tissue sections from deceased asthmatic and non-asthmatic (control) individuals." (PMID 35386975, 2021). "Importantly, GRK2 expression within T cells is required for the manifestation of characteristic features of asthma such as AHR, airway inflammation, IgE and Th2 cytokine (IL-4 and IL-13) production, goblet cell hyperplasia and mucus secretion." (PMID 35386975, 2021). "Additionally, it remains to be determined if the increase in GRK2 expression is accompanied with enhanced GRK2 activity in the lungs during asthma." (PMID 35386975, 2021). "Using GRK2+/− mice (GRK2−/− is embryonically lethal), in the current study, we asked whether GRK2 regulated the development of asthma symptoms induced by HMDE." (PMID 35386975, 2021). "Collectively, our studies reveal an important role for GRK2 in regulating T cell response during asthma pathogenesis and further elucidation of the mechanisms through which GRK2 modulates airway inflammation will lead to the development of new therapeutic strategies for asthma." (PMID 35386975, 2021). "Though these findings underscore the role of GRK2 in regulating responses of different cell types involved in allergic airway disease, to our knowledge there has been no study till date that has examined the role of this adapter molecule in mediating the pathophysiology of asthma." (PMID 35386975, 2021). "To determine the role of T cell-specific GRK2 in affecting the asthma pathology, we generated a mouse stain [CD4 Cre+ GRK2fl/fl (Cre+)] that lacks GRK2 in T cells." (PMID 35386975, 2021). "This suggests that GRK2 is required in the T cell compartment to modulate AHR and serum IgE levels in our asthma model." (PMID 35386975, 2021). "To specifically dissect the contribution of GRK2 in regulating T cell responses during asthma, we generated the CD4 Cre+ GRK2fl/fl mice (that lacked GRK2 in T cells) and exposed these mice to HDME." (PMID 35386975, 2021).
atopic dermatitis (1 paper, 2023). "This raises the interesting possibility that unlike IgE-mediated PCA and itch, GRK2 provides an inhibitory signal for atopic dermatitis through MRGPRX2/B2 desensitization." (PMID 37063868, 2023).
autoimmune cardiomyopathy (1 paper, 2025). An autoimmune form of cardiomyopathy. "Additionally, GRK2 drives M1 macrophage polarization and β1-AR desensitization in autoimmune cardiomyopathy, leading to cardiomyocyte apoptosis." (PMID 40224487, 2025).
autoimmune myocarditis (1 paper, 2025). Autoimmune myocarditis is an autoimmune disease that affects the heart. "In autoimmune myocarditis, macrophages are polarized toward the M1 phenotype, and GRK2 expression is upregulated." (PMID 40224487, 2025). "In conclusion, GRK2 promotes the polarization of M1 macrophages in autoimmune myocarditis and is involved in the desensitization of the β1AR in DCM, leading to apoptosis of cardiomyocytes." (PMID 40224487, 2025).
B-cell lymphomas (1 paper, 2021). "Because KSHV latency is critical for tumor development, these findings suggest that downregulation of GRK2 plays a key role in KSHV-driven B-cell lymphomas." (PMID 33546162, 2021). "We also highlight a newly described role of GRK2 in influencing the pathogenesis of B-cell lymphoma." (PMID 33546162, 2021).
breast luminal cancer (1 paper, 2020). "GRK2 also promotes the HuR/HIF-1α axis and VEGF-C accumulation in normoxic MCF7 breast luminal cancer cells and is required for the induction of HuR/HIF1-α in response to adrenergic stress." (PMID 32413989, 2020).
cardiac arrest (1 paper, 2014). Cessation of breathing and/or cardiac function. "Decreasing CAs levels would permit restoration of cardiac β-AR downregulation/desensitization via cardiac GRK2 downregulation and ameliorate some critical aspects of failing heart such as adverse remodeling, arrhythmias and cardiac arrest." (PMID 25071591, 2014).
ciliopathy (1 paper, 2020). A genetic disorder of the cellular cilia or the cilia anchoring structures, the basal bodies, or of ciliary function. "Because ATD is a ciliopathy, we next examined the affected patient's GRK2−/− patient fibroblasts for defects in ciliogenesis." (PMID 33200460, 2020).
COVID-19 (1 paper, 2024). A disease caused by infection with severe acute respiratory syndrome coronavirus 2. "Our study also identified numerous new kinases, such as DNA-PK, PKG1, ROCK1/, PKCδ, and GRK2, providing additional actional targets for the development of immunomodulatory therapies for COVID-19." (PMID 38389037, 2024).